INS (insulin)
Diseases named in the same sentence as INS in open-access papers (continued):
Sharing a sentence is not in itself a finding about the gene and the disease.
type 2 diabetes (continued). "Effect of Brazil nut and metformin on the blood glucose, serum insulin, HOMA-IR, and glycated hemoglobin levels in fructose/STZ-induced type 2 diabetic rats." (PMID 39239455, 2024). "Our result did not support previous findings that reported higher fecal BA in obese people; higher total energy intake; higher fasting concentrations of TG, insulin, and hs-CRP; and lower f-BA in those with type 2 diabetes." (PMID 38257154, 2024). "Type 2 Diabetes Mellitus (T2DM) is a chronic metabolic disorder characterized by hyperglycemia resulting from insulin resistance and impaired insulin secretion." (PMID 39678196, 2024). "Studies with treatment with GLP-1 analogues in type 2 diabetes have found that the initial postprandial insulin is increased after treatment, and this has been misinterpreted as evidence for a GLP-1 mediated insulin stimulation." (PMID 38890501, 2024). "Post-exercise plasma glucose and insulin have previously been demonstrated to be improved with low-intensity cycle exercise performed under moderate-to-high hypoxia (∼2000–3,000 m) in individuals with overweight and type 2 diabetes (T2D)." (PMID 38903909, 2024). "The patients most studied in long-term trials are type II diabetics who end up with elevated GSH, decreased A1cs, increased fasting insulin levels, and few reports of adverse effects." (PMID 38921002, 2024). "Interestingly, when C-peptide is employed as the denominator for proinsulin ratio computations, it may be a stronger indicator of unstable beta cells and a better predictor of the development of type 2 diabetes than insulin because it is unaffected by variability in hepatic clearance of insulin." (PMID 38654804, 2024). "Insulin resistance (IR), often occurring years before the onset of type 2 diabetes (T2DM), is characterized by a reduced response to insulin, diminishing its effectiveness." (PMID 38254088, 2024). "They emphasized that everyone with type 2 diabetes benefits from periodic CGM, not only patients who receive insulin treatment." (PMID 38660249, 2024). "In order to investigate IGFBP7 expression in islet cells at the protein level, we immunostained pancreatic sections from ND donors and type 2 diabetes donors for IGBFP7, glucagon, and insulin (for donor information)." (PMID 39280605, 2024). "Research on the polygenic animal model of type 2 diabetes, Psammomys obesus, has shown that the expression of SELENOS in the liver is inversely correlated with circulating glucose and insulin levels and directly proportional with plasma TG concentrations." (PMID 38172976, 2024). "Therefore, GATA3 implementation enhances adipogenesis, modifies fat distribution, improves insulin sensitivity, and reduces obesity-related inflammation, supporting its therapeutic relevance in type 2 diabetes (T2D) pathology." (PMID 39768217, 2024). "Alterations in vitamin D receptors may contribute to type 2 diabetes through at least four different pathophysiological pathways:(i) extracellular calcium metabolism, (ii) intracellular calcium in adipocytes, and (iii) insulin secretion regulation, and (iv) cytokine metabolism." (PMID 38233797, 2024). "Insulin stimulation led to increased phosphorylation of Akt-Ser473, AS160-Thr642 and GSK3β-Ser9 in myotubes from both donors with NGT and type 2 diabetes." (PMID 38814443, 2024). "Oral administration of sebacic acid to Type II Diabetics (T2DM) improved glycemic control, improved insulin sensitivity, and reduced hepatic gluconeogenesis and glucose output." (PMID 40452921, 2024). "Using partitioned linkage disequilibrium score regression, we observed enrichment for type 2 diabetes and fasting glucose GWAS loci in promoter-connected putative cis-regulatory elements in EndoC-BH1 cells as well as fasting insulin GWAS loci in SGBS cells." (PMID 39240351, 2024).
type 2 diabetes (continued). "Conversely, it was reported in the context of type II diabetes and fatty liver disease that increased phosphorylation of AKT was an indicator of insulin response and consequently a good prognostic marker for reduced steatosis." (PMID 38216754, 2024). "Expanding our focus to type 2 diabetes (T2DM), insulin therapy also plays a crucial role in its management." (PMID 39065795, 2024). "Indeed, mutations of human glucokinase are seen in a specific subtype of type 2 diabetes (GCK-MODY), which results in a chronic, mild increase in blood glucose levels in part due to decreased glucokinase activity in the pancreas and the associated lower insulin release." (PMID 38967989, 2024). "Fasting blood glucose, fasting insulin, and pancreatic β-cell function correlate with increased concentrations of Br-PFOS.Long-term exposure to PFAS isomers is associated with impaired glucose homeostasis and may increase the prevalence of type II diabetes mellitus among Chinese adults." (PMID 38251002, 2024). "In conclusion, CNOT6L induces hyperglycemia, inflammation and other changes through related miRNA, insulin, PPAR and other related signaling pathways, thus affecting the prognosis of type 2 diabetes." (PMID 39433858, 2024). "The QWINT programme consists of five open-label Phase III RCTs performed in both insulin-naive (QWINT-1 and -2) and insulin-experienced (QWINT-3 and -4) individuals with type 2 diabetes, and individuals with type 1 diabetes (QWINT-5)." (PMID 38679644, 2024). "A randomized controlled trial indicated beneficial effects of magnesium and zinc supplementation on a number of parameters and biomarkers related to the onset of type 2 diabetes and coronary heart disease, including FBG, HDL-C, and insulin levels." (PMID 39125340, 2024). "Another study showed that quercetin induced insulin secretion by directly activating LTCCs in insulin-secreting cell line INS-1, which has potential for controlling type 2 diabetes." (PMID 38773596, 2024). "Moreover, insulin-loaded nanoparticles could relieve on type 2 diabetic mice." (PMID 39458652, 2024). "In a Wistar rat model of type 2 diabetes mellitus (T2DM), daily oral administration of Aronia berry ethanol extract for 8 weeks significantly reduced blood glucose, serum insulin levels, and insulin resistance." (PMID 39194694, 2024). "As expected, the clinical parameters related to type 2 diabetes (FG, HOMA-IR, basal insulin, HbA1c and triacylglycerols) correlated positively with inflammation markers such as hsCRP and the neutrophil and monocyte counts (p<0.01)." (PMID 38981930, 2024). "Glucose-stimulated insulin secretion (GSIS) in pancreatic β-cells is metabolically regulated and progressively diminished during the development of type 2 diabetes (T2D)." (PMID 39442620, 2024). "While ISR and plasma insulin returned to baseline values within ~90 min post meal in the NGT groups, plasma insulin and ISR excursions were prolonged in the type 2 diabetes group." (PMID 39138690, 2024). "There are studies that show that EPA supplementation reduces fasting plasma glucose, insulin, HbA1c, and HOMA-IR levels in patients with type 2 diabetes." (PMID 38612580, 2024). "This study aims to investigate the changes in circulating dipeptidyl peptidase-4 (DPP-4) activity following short-term intensive insulin therapy (SIIT) in newly diagnosed type 2 diabetes (T2D) patients and to assess its potential in predicting long-term remission." (PMID 38476668, 2024). "We observed consistent effects on insulin and glycaemic traits intermediate to type 2 diabetes, with MVMR showing that higher adulthood BMI leads to lower insulin sensitivity and higher insulin secretion." (PMID 37280435, 2023). "In contrast, type II diabetes (T2DM) is instigated by increased insulin resistance in the liver, decreased cell mass of peripheral organs, and insufficient insulin production." (PMID 36978910, 2023).
type 2 diabetes (continued). "The studies also showed decrease in responsiveness to leptin and insulin by these neurons upon chronic feeding of a high-fat diet (HFD), resulting in type-2 diabetes (T2D) and HFD-induced obesity." (PMID 36899905, 2023). "IR is the main factor initiating type 2 diabetes mellitus (T2DM), the most prevalent chronic noncommunicable disease in the world, as IR individuals cannot secrete sufficient insulin to overcome IR‐caused attenuation in glucose disposal." (PMID 38018587, 2023). "Multiple studies have demonstrated that testosterone replacement therapy (TRT) significantly reduces fasting serum glucose (FSG), fasting serum insulin (FSI), and hemoglobin A1C (HBA1C) in hypogonadal patients with type 2 diabetes." (PMID 36961066, 2023). "An important fact is that high insulin and IGF-1 play a significant role in the development of type 2 diabetes and cardiovascular diseases." (PMID 37626790, 2023). "Compared with individuals with type 2 diabetes, those with LADA were less insulin resistant, had worse beta cell function as assessed by HOMA and lower levels of C-peptide, and were more likely to be treated with insulin." (PMID 35900371, 2023). "Type 2 diabetes mellitus (T2DM) is a common chronic disease, characterized by elevated blood glucose and attenuated insulin action." (PMID 37139075, 2023). "Failure to adapt to changes in insulin sensitivity may lead to beta cell dysfunction, which is why the autonomic nervous system has been hypothesised to play an important role in the intricate mechanisms that lead to beta cell dysfunction and, in extension, type 2 diabetes." (PMID 37935826, 2023). "Type 2 diabetes mellitus (T2DM) is characterized by hyperglycemia, hyperlipidemia, and relatively insufficient insulin, which seriously threatens human life and health." (PMID 37836402, 2023). "Type 2 diabetes mellitus (T2DM), a metabolic disorder characterized by imbalanced blood sugar levels, is thought to be precipitated by a combination of impaired insulin secretion and insulin resistance." (PMID 36650599, 2023). "Among three types of liposomes, HDCA:ME-(1:1)-Lips significantly reduced the fasting blood glucose levels, improved glucose tolerance, and regulated biochemical indices (TC, TG, INS, GLP-1, SOD, CAT, and MDA) in type 2 diabetic mice." (PMID 36985444, 2023). "It has been proposed that LC-CoA accumulation in pancreatic β-cells in type 2 diabetes promotes KATP channel opening and reduces glucose sensitivity of insulin secretion." (PMID 37735536, 2023). "Concomitantly, in humans, new generation insulin sensitizers MSDC‐0160 and MSDC‐0602K targeting MPC have been in clinical trials for type II diabetes." (PMID 37366179, 2023). "Although more patients with type 2 diabetes at baseline underwent RYGB, patients who underwent SG showed similar improvements in glycemic control and insulin resistance, and both surgical procedures significantly improved lipid parameters." (PMID 37414579, 2023). "In comparison to type 2 diabetes (T2D), individuals with LADA have lower insulin secretion and a faster progression to insulin dependency; furthermore, islet autoantibodies are biomarkers of autoimmune beta-cell destruction that distinguish LADA from T2D1." (PMID 37120620, 2023). "The insulin response to an OGTT is also increased in both healthy participants and in type 2 diabetics." (PMID 37111160, 2023). "Conversely, type 2 diabetes (T2D) arises from increased tissue resistance to insulin action." (PMID 37958659, 2023). "The increased demand on pancreatic β-cell to produce and secrete more insulin may eventually lead to β-cell dysfunction, which is the key factor in the development of type 2 diabetes mellitus (T2DM), and is characterised by persistent hyperglycemia." (PMID 37498860, 2023).
type 2 diabetes (continued). "Collectively, our results demonstrate that selective SSTR5 inhibition can improve insulin sensitivity by enhancing liver insulin action; thus, selective SSTR5 antagonists represent potentially novel therapeutic agents for type 2 diabetes." (PMID 36585794, 2023). "It has been revealed that Creb3l4 knockout mice exhibit glucose tolerance and decreased insulin sensitivity, suggesting a role of CREB3L4 in both obesity and type 2 diabetes." (PMID 37569434, 2023). "Type 2 diabetes mellitus (T2DM) is an endocrine disorder characterized by high levels of blood glucose and dysfunction of insulin secretion." (PMID 37582714, 2023). "Engineered nanomaterials (ENMs) may decrease insulin sensitivity and damage pancreatic beta (β)‐cells, thus changing glucose homeostasis, which might lead to type 2 diabetes mellitus (T2DM)." (PMID 35287244, 2023). "GoProcess annotation revealed that most of these effects were concentrated on processes related to “regulation of lipid metabolism”, “insulin-dependent stimulation of SREBP-1 in type 2 diabetes in liver”, and “role of ER stress in obesity and type 2 diabetes”." (PMID 37982029, 2023). "Combination therapy using the complementary mechanisms of action of basal insulin and GLP-1 RA targets seven of the many pathophysiologic defects in type 2 diabetes, adressing both FPG and PPG." (PMID 36726134, 2023). "Type 2 diabetes (T2DM) is a chronic metabolic disease that clinically manifests as hyperglycemia and insufficient insulin secretion." (PMID 37250902, 2023). "Insulin secretory responses (insulin and C-peptide rises above baseline) during the administration of exogenous human synthetic GIP were uniformly much smaller in those with type 2 diabetes than in healthy individuals." (PMID 37430117, 2023). "For patients with type 2 diabetes (T2D), calculating the daily dose of basal insulin may be challenging." (PMID 36749650, 2023). "We speculate that the increase of the irisin concentrations in an insulin resistance microenvironment might be a compensatory mechanism to attempt the recovery of the glucose homeostasis, promoting the glucose uptake and consequently, preventing the development of type 2 diabetes." (PMID 37448465, 2023). "Collectively, these results showed that ER stress marker genes are also significantly related to increased insulin demand and worsening of glucose metabolism in IGT and type 2 diabetes patients." (PMID 36280617, 2023). "In type 2 diabetic human patients, PTP1B inhibition also resulted in a remarkable reduction in fed and fasted glucose and HbA1c levels parallelly to lowered insulin blood levels, in relation to an improved adiponectin secretion." (PMID 37020593, 2023). "In obese patients or patients with type II diabetes, circulating IGFBP-2 levels are low, while the overexpression of IGFBP-2 protects against the disease by inhibiting adipogenesis and modulating insulin sensitivity." (PMID 37509659, 2023). "Lipid metabolism functions in Adipose tissue is a simple surrogate measure that represents pathophysiological changes in adipose tissue insulin sensitivity, with increasing change from normal weight to obesity and from NGT to type 2 diabetes." (PMID 37047308, 2023). "In patients with type 2 diabetes, decreased HSP72 gene expression in muscles is correlated with decreased tissue insulin sensitivity." (PMID 36978903, 2023). "The body of research suggests that incorporating legumes and pulses into the diet not only influences glycaemic markers but also has notable effects on insulin levels and HOMA-IR scores in individuals with type 2 diabetes." (PMID 37836506, 2023). "Type 2 diabetes is characterized by the inability of insulin to inhibit glucose output from the liver and to promote glucose uptake in adipose and muscle tissues; a new term ‘diabesity’ is used to refer to T2D which occurs due to obesity." (PMID 37103396, 2023).
type 2 diabetes (continued). "Although GIP secretion can remain near‐normal in individuals with type 2 diabetes, the insulin response to GIP is markedly impaired; in contrast, the insulin response to GLP‐1 is preserved." (PMID 37602910, 2023). "Type 2 diabetes, cardiovascular disease, dyslipidemia, fatty liver and obstructive sleep apnea are seen 2–3 times more frequently in women with PCOS with high insulin and BMI values compared to normal women." (PMID 38813505, 2023). "Two types of fixed-ratio combinations of basal insulin and a glucagon-like peptide-1 receptor agonist (GLP-1RA) have been approved for use in type 2 diabetes." (PMID 36726134, 2023). "Type 2 diabetes mellitus (T2DM) is a metabolic disease characterized by impaired glucose metabolism, resulting from insulin resistance or impaired insulin secretion." (PMID 38110464, 2023). "Fat ingestion before a carbohydrate meal slows gastric emptying, delays the postprandial rises in blood glucose, plasma insulin, and GIP, and stimulates GLP-1 secretion in type 2 diabetes." (PMID 36986224, 2023). "Hepatic insulin clearance (HIC) is considered an important pathophysiology of hyperinsulinemia, metabolic syndrome, and type 2 diabetes." (PMID 38115089, 2023). "Numerous studies have demonstrated that testosterone therapy improves systolic and diastolic blood pressure, lipid profiles, insulin sensitivity, inflammation, fasting plasma glucose (FPG), and glycated hemoglobin (HBA1c) levels in men with type 2 diabetes." (PMID 36961066, 2023). "Insulin signaling is negatively regulated by protein tyrosine proteases 1B (PTPs), that negatively regulates the insulin pathway, inter alia, through JAK2-STAT3 axis, which is dysfunctional in types 2 diabetes and obesity." (PMID 37808009, 2023). "Nevertheless, in a subgroup analysis of people with type 2 diabetes, both patients with MACS and Cushing’s syndrome required insulin treatment more frequently than patients with NFAI (aPRs, 1.89 (CI, 1.01 to 3.52) and 3.06 (CI, 1.60 to 5.85), respectively)." (PMID 38137336, 2023). "In people with prediabetes or early type 2 diabetes, MFDM elicited reduced glucose and insulin responses when compared with SF." (PMID 37293492, 2023). "Type 1 diabetes (T1D) is an autoimmune disease that causes specific destruction of pancreatic β-cells, leading to low or no insulin secretion into the bloodstream, while type 2 diabetes (T2D) is characterized by an insufficient response to insulin by tissues of the body, known as insulin resistance." (PMID 37817156, 2023). "In type 2 diabetic rats, treatment with PAP1 normalized blood glucose levels, insulin resistance, abdominal fat accumulation, and dyslipidemia." (PMID 34623540, 2023). "In people with type 2 diabetes, HIIT improves skeletal muscle oxidative capacity, glycemic management, and insulin sensitivity." (PMID 37445852, 2023). "However, since insulin treatment should be avoided while treating elderly type 2 diabetes patients to reduce the risks of hypoglycemia, a combination of SGLT2 inhibitors, GLP-1 agonists, and other kinds of OHA might be necessary to reach appropriate sugar levels." (PMID 37036483, 2023). "Type 2 diabetes (T2DM) is a chronic, progressive metabolic disorder characterized by deteriorative hyperglycemia following impaired insulin secretion and utilization." (PMID 36359885, 2022). "The outcomes of this research are compatible with recent studies and have established that HIIT in type 2 diabetes results in more improvements in body mass, BMI, 2 h-PG, TC, TG, HDL, LDL, insulin secretion, HbA1c and HOMA-IR Compared to other groups." (PMID 36404859, 2022). "The atypical β cell cluster in the anti–PD-L1–treated mice expressed genes involved in pathways of maturity-onset diabetes of the young (MODY) as well as T1D, insulin processing, and ER function." (PMID 35925682, 2022).